PRL (prolactin)
Diseases named in the same sentence as PRL in open-access papers (continued):
Sharing a sentence is not in itself a finding about the gene and the disease.
cancer (continued). "Prolactin (PRL) and its receptor (PRLR) are also important in CC; previous reports of our group of research have shown that PRLR expression in cervical tissue is increased as the disease advances towards cancer." (PMID 31507337, 2019). "Furthermore, nine cancer biomarkers: MIF, TNFα, sFasL, TRAIL, FGF2, SCF, prolactin and OPN, were negatively correlated to Lactobacillus abundance and positively correlated to levels of vaginal pH." (PMID 31089160, 2019). "Finally, the phosphatase of regenerating liver (PRL) phosphatases, that are able to stimulate ERK1/2 and Akt signaling and are overexpressed in many cancer types, also depend on oligomerization for their activity." (PMID 29439552, 2018). "To determine the outcome of upregulation of miR-106b in cancer, we first examined effects on relative cell number, as assessed by MTS assay, with increased expression of miR-106b or anti-miR106b in the absence or presence of prolactin." (PMID 28422740, 2017). "Out of the models containing “hormone blood level” and “tissue group” a relationship was only found for PRLR mRNA expression: PRL blood levels had a negative relationship with PRLR gene expression only in malignant neoplasms (p = 0.025)." (PMID 26370564, 2015). "A number of studies have found that prolactin actively participates in tumorigenesis and that it is overexpressed in several cancer cell lines including those derived from reproductive and non-reproductive tissues." (PMID 25987887, 2015). "We show here that serum prolactin levels are strongly influenced by the conditions of blood collection and that prolactin does not discriminate between cancer and non-cancer patients in serum specimens collected similarly in a clinic setting." (PMID 18060075, 2007). "In addition, evidence exists that human PRL-antagonists, such as HPRL-G129R, can inhibit cancer cell proliferation through induction of apoptosis." (PMID 12698200, 2003). "Plasma prolactin concentrations were also found to be higher in cancer compared with non-cancer patients, this effect being more marked in premenopausal than in postmenopausal patients." (PMID 3756079, 1986). "In addition to some conventional demographic and clinicopathological factors, a cluster of verified cancer‐related prognostic factors, including AGR, NLR, PLR, PRL, LDL, and PNI, may be used to establish nomograms." (PMID 34128338, 2021). "Finally, some infections can also regulate the PRL/PRLR axis, thus regulating cancer promotion." (PMID 34745013, 2021). "Although EVE has been widely used in the management of pancreatic and other neuroendocrine neoplasms, there are only seven published cases of pituitary tumors treated with EVE combination therapy (three ACTH secreting carcinomas, one PRL secreting adenoma, and three not stated)." (PMID 33841328, 2021). "Interestingly, a subset of identified cancer biomarkers (TNFα, sFasL, TRAIL, prolactin, FGF2, SCF, OPN), which were identified in the high diversity/inflammation cluster, were also correlated with Lactobacillus abundance, vaginal pH and genital inflammation and were elevated in the ICC group." (PMID 31089160, 2019). "There is a great deal of overlap between CCND2, G1/S-specific cyclin D2, and STAT3, including the prolactin and FOXO signaling pathways, which are inactivated by major oncogenic signals such as the PI3K and MAPK pathways, and their expression is also repressed by microRNAs in multiple cancer types." (PMID 29992138, 2018). "Interestingly, signals through this pathway are required for initiation, but not progression, of PRL-induced cancers in NRL-PRL females." (PMID 28103936, 2017). "A possible explanation may be that PRL can also signal through other effectors, including Focal Adhesion Kinase (FAK), Src-Family Kinases (SFKs), and ERK1/2, which may enable aggressive luminal cancers to co-opt PRL signals for pro-tumorigenic purposes." (PMID 27344177, 2016).
cancer (continued). "On the other hand the serum levels of ADIPOQ, CXCL9, PECAM-1, Prolactin, sVEGFR-1 and sVEGFR-2 in the T2D-HCC patients were higher than those of patients with only T2D while they were similar to those of HCC patients, confirming that these proteins are specific for the cancer presence." (PMID 26226632, 2015). "PRLRs observed in tumors could maximize action(s) induced by endogenous prolactin through its receptor and be an important factor in cancer progression in the absence of E2." (PMID 25193864, 2014). "Interestingly, unlike non-transformed mammary epithelial cells, TG2 expressing cancer cells were unable to undergo differentiation in response to prolactin treatment." (PMID 21687668, 2011). "We hypothesise that the identification of these genes should yield insights into the mechanisms by which prolactin participates in cancer formation or progression, and possibly how it regulates normal mammary gland development." (PMID 19014541, 2008). "However, we showed that minor elevations of prolactin which do not affect the sexual behaviour of males, produced significant changes at the prostate epithelium that could account for triggering the development of hyperplasia or cancer." (PMID 16707016, 2006). "While PRL is an important regulator of fatty acid metabolism in normal human breast epithelial cells and adipose tissue and is locally produced in the breast, its role in mediating β-oxidation via CPT1 in cancer cells has not been explored." (PMID 21294903, 2011). "Notably, these cancer biomarkers functionally comprised of several cytokines (IL-6, MIF, TGF-α, TNFα), apoptosis-related proteins (sFas, sFasL, TRAIL), growth and angiogenic factors (FGF2, HGF, SCF, VEGF), hormones (leptin, prolactin) and other biomarkers (AFP, OPN), but not carcinoma antigens." (PMID 31089160, 2019).
infection (46 papers, 2007 to 2025). The state of being infected such as from the introduction of a foreign agent such as serum, vaccine, antigenic substance or organism. "The pharmacological blockage of PRL synthesis during the whole courseof infection caused an additional increase of circulating corticosterone and a more severe thymusatrophy, when compared to infected animals that received vehicle alone." (PMID 24324845, 2013). "High prolactin serum levels have been associated with seronegativity to Toxoplasma gondii, which is capable of directly binding to the parasite and restricting intracellular growth and competent infection (reviewed in reference 38)." (PMID 36786574, 2023). "This could be related to the fact that cows in this period have a high level of prolactin and progesterone, altering their immune system and making them more susceptible to infection." (PMID 35456078, 2022). "In summary, the relationship between PRL levels and COVID‐19 outcomes underscores a dual role where elevated serum PRL can either protect against or worsen the effects of the virus, depending on the infection phase and the patient’s underlying health conditions." (PMID 41476991, 2025). "However, the presence of higher levels of prolactin and progesterone hormones could make females more susceptible to any infection." (PMID 37214158, 2022). "Infection by HCMV is known to interact with the prolactin (PRL)/PRLR axis to promote inflammation and potentially contribute to tumorigenesis." (PMID 41463341, 2025). "Taken together, these findings indicate that infection with virulent Brucella strains alters the secretome of decidualized stromal cells, affecting not only prolactin production but also enhancing the secretion of proinflammatory chemokines." (PMID 40943115, 2025). "Prior infection with Brucella significantly reduced PRL production in a multiplicity of infection (MOI)-dependent manner at 6 days post-decidualization compared to non-infected cells." (PMID 40943115, 2025). "Studies conducted both in vitro and in vivo have identified PRL regulatory element binding (PREB) as a novel cofactor in the infection process of HCV." (PMID 41476991, 2025). "Understanding the impact of the infection also on serum PRL, E2, and SHBG levels would be useful to have a more complete picture of the pathogenetic mechanisms through which the infection causes testicular dysfunction." (PMID 38345682, 2024). "The nature of this synaptic connection was further examined by patch-clamp recording of PrL neurons under ex vivo optogenetics stimulation, with prior ChR2 infection into BLASCT+ neurons." (PMID 36845323, 2023). "It is well established that the elevation of prolactin levels is a form of response to various stresses, including infections." (PMID 37790604, 2023). "At the 14th days post-infection (dpi) infected with Trypanosoma cruzi (T. cruzi), PRL treatment increases the percentage of natural killer (NK) cells and B lymphocytes in the rat spleen compared to the infected without PRL treatment and the untreated group." (PMID 35910654, 2022). "PRL transcript levels tended to be slightly higher in infected cells pretreated with PRL 3 h before infection compared with untreated infected cells." (PMID 32121009, 2020). "Across five animals, some degree of infection was measured in 12 distinct areas, namely FrA, PrL, MO, VO, LO, DLO, OB, M1, M2, CgI, AI and EX." (PMID 32096761, 2020). "It seems that the higher level of prolactin and progesterone hormones enhances the vulnerability of the females to any infection." (PMID 32846897, 2020). "PRL transcript levels were further increased in infected cells that were pretreated with PRL 3 h before infection." (PMID 32121009, 2020). "During infection and inflammation, PRL plays a critical role in maintaining the immune system homeostasis." (PMID 33132594, 2020).
infection (continued). "Here we show that both, E2 and PRL, have the capacity to increase the expression of E6 and E7 oncogenes in SiHa and HeLa cells that have an infection by HPV 16 and 18, respectively." (PMID 31507337, 2019). "An increased PRL concentration can be observed due to infection in the Intact and Sh-HPRL groups compared with the control (P<0.05)." (PMID 29921576, 2018). "The results showed a differential effect of PRL and infection on different immune compartments in the percent of total T cells, T helper cells, T cytotoxic cells, B cells, NK cells, and Tγδ cells." (PMID 29921576, 2018). "In conclusion, the results obtained concerning PRL involvement and infection effect on the immune system differed depending upon the surgical treatment to which the rats were subjected." (PMID 29921576, 2018). "MET administration, which inhibitsdopaminergic receptors located in the hypothalamus, did recover PRL systemic levels, showing thatthe control mechanisms of PRL secretion by the pituitary gland are preserved during infection." (PMID 24324845, 2013). "Earlier work indicated that infection with canonical MMTV resulted in an enhanced response of the host mammary tissue to exogenous prolactin." (PMID 23866257, 2013). "For this, we adrenalectomized mice (ADX) one week prior to infection, in order to remove GCsystemic contents, and then analyzed the PRL levels and thymuses of the animals." (PMID 24324845, 2013). "Immunofluorescence analyses indicate that medullary thymic epithelial cells are the mainintrathymic source of PRL during acute infection." (PMID 24324845, 2013). "In addition to glucocorticoids, there are other factors such as galectin-1, prolactin, progesterone, and IL-10 have been reported to inhibit infection-induced inflammatory responses in the intrauterine tissues." (PMID 39290694, 2024). "Furthermore, we showed that injection of metoclopramide (known to enhance PRL secretion by the pituitary gland), during experimental infection, preserved the thymus from atrophy during infection with T. cruzi." (PMID 29963015, 2018). "Following an overnight infection, cells were treated with 5 μg/mL prolactin for 24 or 48 hours." (PMID 26799659, 2016). "In an attempt to check a possible cross-talk between PRL- and GC-mediatedcircuits, we analyzed if the decrease of PRL secretion during infection could be related to the GCrise." (PMID 24324845, 2013). "In addition to higher BMI, higher FSH/LH ratio, lack of reduction of prolactin levels, and skin involvement, other risk factors for recurrence include smoking (OR=48.5) and infection with Corynebacterium kroppenstedtii (OR=32.2)." (PMID 39205744, 2024). "Moreover, infection affects prolactin secretion and male sex hormone levels." (PMID 37790604, 2023). "In summary, PRL selectively regulates the first wave of inflammatory factors (cytokines and chemokines), decreases the second wave of degradative factors, favors an environment compatible with immune privilege, and partially controls the deleterious response during infection." (PMID 37359537, 2023). "Interestingly, we found and unexpected observation: PRL level raised after the infection." (PMID 29921576, 2018). "The secretion of prolactin could be disturbed by an immune stress commonly accompanying infection." (PMID 30186037, 2018). "In conclusion, after infection with ALV-J, the levels of PRL, GH, IgG, and IgM in the serum and the expression of some immune-related genes in the spleen were different between LF and EF chickens." (PMID 34998433, 2022). "In addition, kidneys also showed up-regulated endocrine networks involved in estrogen, prolactin, and insulin signaling pathways and thyroid hormone synthesis, supporting the bi-directional crosstalk between endocrine and immune systems in response to pathogen infection." (PMID 35163263, 2022).
infection (continued). "To date, this is the first study to characterize the rumen microbiota and its relationship with serum prolactin and NEFA in gestating and lactating ewes grazing tall fescue with high or moderate levels of toxic endophyte infection." (PMID 33173791, 2020). "In GH-/PRL-secreting GH3 cells, the infection with T. cruzi in vitro induces a reduction in the secretion of both GH and PRL." (PMID 29963015, 2018). "The findings made by the present study concerning the role of PRL over the percentages of cell subpopulations differs depending upon the type of surgery utilized, the analyzed organs (spleen, PLN, MLN) and infection status." (PMID 29921576, 2018). "Furthermore, in the current model active Ct infection, but not exposure to either UV-inactivated organisms or to purified E. coli or S. Minnesota LPS, caused a reduction in mRNA and protein levels of the widely used phenotypic decidualisation marker, PRL." (PMID 28515460, 2017). "PRL pretreatment of cells starting 3 h before or at the time of infection did not alter PRLR transcript levels." (PMID 32121009, 2020). "The infection with either wild type B. abortus or the btpAbtpB mutant did not modify the levels of LDH or prolactin as compared to non-infected cells at any time point, showing that it does not induce cytotoxicity or affect the decidualization of cells." (PMID 32408491, 2020). "Our results show that the percentage of NK cells was independent of plasmatic PRL concentration, although we did find increased percentages due to infection in some experimental groups." (PMID 29921576, 2018). "Infection with Ct, but not treatment with UV-inactivated Ct, reduced the expression of the classic decidualisation marker prolactin (PRL) at both mRNA and protein levels in decidualised Ct infected ESC." (PMID 28515460, 2017). "Although GTC implantation was not affected upon B.suis.S2 infection, progesterone secretion was suppressed, and prolactin and estrogen secretion increased; these effects were accompanied by changes in the expression of genes encoding key steroidogenic enzymes." (PMID 26904517, 2016). "Infection by Gram-negative bacteria and their cell wall component, lipopolysaccharide (LPS), has been shown to inhibit production of prolactin in the pituitary gland, mediated by TNF." (PMID 27119014, 2016). "Following infection of CID-9 cells with Ad-DN-STAT5, prolactin stimulation still resulted in phosphorylation of STAT5 at tyrosine residue 694 at 24 and 48 hours; however, due to the deletion of the transactivation domain, prolactin induced PAD3 expression was blunted at 48 hours." (PMID 26799659, 2016). "The thyroid axis, gonadal and lactotropic axis were normal, so were the level of FT3, FT4, STSH and LH, FSH, T, E2 as well as PRL in these two cases we studied because they were in prolonged but not acute phase of infection." (PMID 24472299, 2014). "During infection, adrenalectomy protectedthe thymus from the increase in apoptosis ratio without changing PRL levels, whereas an additionalinhibition of circulating PRL accelerated the thymic atrophy and led to an increase incorticosterone systemic levels." (PMID 24324845, 2013). "Nevertheless, nothing was known concerning the role of PRL uponthe systemic increase of GCs during infection, nor the possible impact upon thymus atrophy." (PMID 24324845, 2013). "The timing of sample collection, although standardized, may not fully capture the dynamic fluctuations of prolactin and cytokine levels during the course of infection, thus limiting the ability to draw conclusions regarding temporal changes." (PMID 39595974, 2024). "To understand the difference in immune responses between EF and LF chickens after infection with ALV-J, we detected the levels of PRL, GH, IgG, and IgM in the serum of positive and negative individuals of these two types of chickens for eight consecutive weeks." (PMID 34998433, 2022).
infection (continued). "After infection with ALV-J, it is not clear whether the levels of the two hormones PRL and GH and the two immunoglobulins IgG and IgM in the serum and the expression of some immune-related genes in the spleen differ between LF and EF chickens." (PMID 34998433, 2022).